B2M (beta-2-microglobulin)
Diseases named in the same sentence as B2M in open-access papers (continued):
Sharing a sentence is not in itself a finding about the gene and the disease.
Pleural effusion (1 paper, 2012). The presence of an excessive amount of fluid in the pleural cavity. "A second trial evaluated 50 patients with stage II to IV FL and low tumour burden (no nodal or extranodal mass > 7 cm, B symptoms, splenomegaly, pleural effusion, ascites, organ compression, and elevated serum lactate dehydrogenase or beta-2-microglobulin)." (PMID 22650448, 2012).
primary progressive MS (1 paper, 2018). "A third orthologue, B2M was also upregulated in relapsing versus primary progressive MS." (PMID 30114292, 2018).
Pruritus (1 paper, 2023). Pruritus is an itch or a sensation that makes a person want to scratch. "A higher frequency of pruritus (p = 0.008) and higher peripheral blood levels of beta-2 microglobulin (p ≤ 0.001) and lactate dehydrogenase (p = 0.025) were found in CTCLs compared to those of CBCLs." (PMID 37999132, 2023).
pulmonary edema (1 paper, 2024). Accumulation of fluid in the lung tissues causing disturbance of the gas exchange that may lead to respiratory failure. "Rats with high-altitude pulmonary edema had significantly lower levels of B2M expression compared to control rats, which showed consistency with the bioinformatics analysis and could be considered as a biomarker of high-altitude pulmonary edema." (PMID 37165489, 2024). "Studies have shown that B2M expression levels do not appear to be affected by hypoxia, as hypoxia is not the cause of B2M degradation and may be used as a specific biomarker for early screening, treatment and prognosis of highland pulmonary edema in plateau areas." (PMID 37165489, 2024).
pulmonary fibrosis (1 paper, 2023). Chronic progressive interstitial lung disorder characterized by the replacement of the lung tissue by connective tissue, leading to progressive dyspnea, respiratory failure, or right heart failure. "Increased serum beta-2-microglobulin (B2M), the light chain of the class I major histocompatibility complex, has been linked with COPD disease progression, namely development of pulmonary fibrosis, alveolar wall thickening and decreased gas exchange capacity." (PMID 37474963, 2023).
rectal tumors (1 paper, 2020). "Five promising reference genes GAPDH, Pumilio RNA binding family member 1 (PUM1), beta-2-microglobulin (B2M), ribophorin I (RPN1), and phosphomannomutase 1 (PMM1) were selected from different publications to assess their expression stability in rectal tumors as part of the screening phase." (PMID 33457124, 2020).
retinal degeneration (1 paper, 2025). Degeneration of the retina. "B2m is upregulated in microglia during retinal degeneration in rats, and promote neurodegeneration as a component of MHC class I in an amyotrophic lateral sclerosis mouse model." (PMID 41056359, 2025).
retinoblastoma (1 paper, 2002). A malignant tumor that originates in the nuclear layer of the retina. "Twenty-five primary retinoblastoma tumours were analysed by real-time quantitative polymerase chain reaction to determine the genomic copy number of the N-MYC gene (2p24) relative to the copy number for REL, B2M, ALB, AF10 and MLL." (PMID 12232763, 2002).
rhabdomyosarcoma (1 paper, 2023). A rare aggressive malignant mesenchymal neoplasm arising from skeletal muscle. "In addition, B2M LOH (without CN-LOH, LOH+gain or amplification) was detected in 18 (3.9%) tumors, including six (11.8%) rhabdomyosarcoma cases." (PMID 38318504, 2023).
status epilepticus (1 paper, 2013). Status epilepticus is defined as a continuous seizure lasting more than 30 min, or two or more seizures without full recovery of consciousness between any of them. "The validation of these data by the analysis of the relative expression of Gfap showed that the upregulation of the Gfap gene in the hippocampus of rats sacrificed 24 hours after status epilepticus (SE) was undetected only when B2m was used as the normalizer." (PMID 24009668, 2013).
synovial sarcoma (1 paper, 2017). "Furthermore, we found that synovial sarcoma, which overexpresses PRAME, showed a significantly lower B2M and CD8A expressions compared to other subtypes." (PMID 28630682, 2017).
T-cell lymphomas (1 paper, 2015). "Mutation of B2M was implicated in impaired DNA damage response and escape from the immune surveillance mechanisms of T-cell lymphomas." (PMID 25622250, 2015).
tauopathy (1 paper, 2024). Neurodegenerative disorders involving deposition of abnormal tau protein isoforms (tau proteins) in neurons and glial cells in the brain. "However, in the tauopathy mouse model, further experimental investigation is required to validate the neurodegenerative effects attributed to tauopathy-associated CD8+ T cells, such as exploring tauopathy in B2m-deficient TE4 mice." (PMID 38355649, 2024).
temporal lobe epilepsy (1 paper, 2024). A localization-related (focal) form of epilepsy characterized by recurrent seizures that arise from foci within the temporal lobe, most commonly from its mesial aspect. "Therefore, the increase in B2m mRNA during the latent phase in the lithium–pilocarpine temporal lobe epilepsy model may be due not only to changes in transcription levels but also to an increase in the number and/or activation of microglia." (PMID 38791067, 2024). "No changes were detected in B2m expression in the striatum (Figure A4), which is believed to have an inhibitory effect and not generate epileptiform activity in temporal lobe epilepsy." (PMID 38791067, 2024).
thrombosis (1 paper, 2022). "This difference in the levels resulted in a higher prevalence of B2M-CIC-positive patients with isolated gestational morbidity in relation to patients with thrombosis." (PMID 36172349, 2022). "The difference observed in B2M-CIC levels resulted in a higher prevalence of B2M-CIC-positive patients with isolated gestational morbidity (44.8%) in comparison with patients with isolated thrombosis (29.6%, p=0.023) and mixed APS (25.0%, p=0.042)." (PMID 36172349, 2022). "It stands out that there was a significantly higher proportion of B2M-CIC-positive patients among those with obstetric APS without a history of thrombosis (isolated gestational APS)." (PMID 36172349, 2022).
thyroid cancer (1 paper, 2021). "B2m has been identified as a potential biomarker for thyroid cancer, kidney disfunction and renal disease." (PMID 34315405, 2021).
viral meningitis (1 paper, 2019). Inflammation of the membranes surrounding the brain and spinal cord due to a viral infection. "An additional study described the utility of simultaneous evaluation of ferritin and B2M levels as an ancillary tool in the differential diagnosis of bacterial and viral meningitis." (PMID 31063510, 2019).
tumor (464 papers, 1985 to 2026). "In two instances, resistance-associated mutations in B2M or JAK2 were detected as subclonal events in the pre-treatment tumor and clonal in the resistant tumor." (PMID 39933900, 2025). "A β2 microglobulin (B2M) deficiency due to mutation results in reduced level of MHC I on the surface of tumor cells." (PMID 40725022, 2025). "γδT cells can function as critical effectors in ICIs therapy against HLA-I/B2M-deficient cancers, representing a novel mechanism and therapeutic strategy for monitoring tumor immune escape." (PMID 40191187, 2025). "The Beck research team, by establishing a B2M-deficient mouse tumor model, revealed that MHC-I deficiency would result in severe immune desertification in TME and widespread resistance to ICIs." (PMID 40191187, 2025). "Tumor-specific CD8+ T lymphocytes are unable to detect tumor cells because of mutations in the B2M gene." (PMID 40038799, 2025). "Beyond the existing FLIPI parameters, the FLIPI2 study explored the inclusion of β2-microglobulin (B2M), a protein associated with lymphocyte activity and a potential marker of tumor burden and cell turnover." (PMID 40075894, 2025). "Key mechanisms of resistance include loss of MHC expression, B2M gene mutations, tumor cell de-differentiation, and disruptions in signaling pathways such as PTEN." (PMID 40725022, 2025). "B2M mutation/defect can significantly diminish the recognition of cancer cells by lymphocytes, thereby inducing tumor immune evasion and resistance to immunotherapy." (PMID 40191187, 2025). "In a study on the response of mismatch repair-deficient tumor patients to PD-1 blockade therapy, a total of five cases of drug resistance were observed, among which two patients were detected with B2M gene mutations." (PMID 41514551, 2025). "Local injection of oncolytic viruses holds the potential to overcome ICIs resistance attributed to B2M mutation and enhances anti-tumor responses through activating the IFN-γ/JAK/STAT signaling axis." (PMID 40191187, 2025). "At the genetic level, B2M mutation facilitates tumor immune evasion through hampering antigen presentation." (PMID 40191187, 2025). "Accumulating evidence indicates that B2M mutation/defect is one of the key mechanisms underlying tumor immunotherapy resistance." (PMID 40191187, 2025). "B2M mutation/defect can impair antigen presentation, which constitutes a significant factor of tumor immunotherapy resistance." (PMID 40191187, 2025). "Another strategy is immune evasion through the downregulation of potential tumour associated antigens, for example via the downregulation of B2M, which is involved in antigen presentation." (PMID 38773187, 2024). "Deletion of tumor cell B2m results in the loss of MHC class I, thereby preventing tumor recognition and elimination by CD8+ T cells." (PMID 38427670, 2024). "In this study, one CTLA4res case had a frameshift deletion and two PD1res lesions had deep deletions of B2M that consequently also had loss of the B2M protein in the tumor cells." (PMID 38594286, 2024). "Studies have also identified the loss of β2-microglobulin (B2M) as a potential molecular pathway of tumor cells to evade immunity." (PMID 38629578, 2024). "The results of our IHC staining demonstrated that HLA-A and B2M protein loss occurred between 0-56% in diverse tumor types and subtypes with a higher frequency of B2M and HLA-A loss in metastatic specimens." (PMID 38455061, 2024). "Low B2M gene expression was significantly associated with high-grade tumor histology in RB1-loss tumors." (PMID 38751776, 2024). "In conclusion, our results substantiate that B2M and HLA-A protein loss occurs at varying frequencies over different tumor types." (PMID 38455061, 2024). "Loss-of-function mutations or LOH195 of MHC-I and beta-2-microglobulin (B2M) are frequently enriched across tumours and the adaptive immune system promotes evolutionary selection by killing tumour cells that present immunogenic antigens." (PMID 38183840, 2024).
tumor (continued). "B2M is a crucial element of the human leukocyte antigen-I (HLA-I) complex, and tumor B2M deletion is associated with immune evasion, which is one of the adverse prognostic factors in various cancers." (PMID 39802954, 2024). "B2M and HLA loss in tumor cells has been extensively studied from a molecular and mechanistic perspective and its potential implications for cancer immunotherapy." (PMID 38455061, 2024). "We envision that our findings on influence of B2m extend beyond the hematopoietic system, impacting tumor-associated macrophages (TAMs) and anti-CD47 treatment efficacy in tumors with high MHC-I." (PMID 39264994, 2024). "We observed that loss of B2m significantly rescued the progression of tumors derived from Pikfyve-null cancer cells, supporting that the tumor control mediated by Pikfyve-loss was also mediated by tumor-specific MHC-I expression." (PMID 38011559, 2023). "To extend this finding to additional contexts associated with immune checkpoint blockade resistance, we next evaluated B2m-deficient B16 tumours and KPC tumours and observed a response to AC484 treatment in both models." (PMID 37794185, 2023). "A study of lung cancer with 14 ICB-resistant tumor samples also revealed the homozygous loss of B2M in a patient who acquired resistance to combined anti-PD-L1 and anti-CTLA-4 therapy." (PMID 37614504, 2023). "In conclusion, among several other markers assessed in multiple tissue compartments, B2M expression in tumor cells exhibited a strong association with immunotherapy outcomes in R/M HNSCC, an effect that was reproduced in an additional, validation cohort." (PMID 37057033, 2023). "The MHC class I molecule presents tumor antigens to T cells, and any disruption in this pathway, as caused by B2M mutations, can lead to ineffective T cell-mediated tumor cell lysis." (PMID 38136402, 2023). "Immunohistochemical analysis confirmed the loss of B2M protein expression on tumour cells in all mutated cases." (PMID 36631610, 2023). "Next, B2M expression in tumor was quantified and explored for associations with survival, by QIF on a second, independent, validation cohort of R/M HNSCC cases (Yale cohort, YTMA523)." (PMID 37057033, 2023). "The levels of other immune cells, including NK cells, CD4+ T cells and CD8+ T cells, were similar between B2M-deficient and B2M-proficient tumours." (PMID 36631610, 2023). "In the current study, DSP revealed the positive association of B2M expression in the tumor compartment with immunotherapy outcomes in R/M HNSCC." (PMID 37057033, 2023). "Loss of antigen-presenting machinery components such as beta-2-microglobulin and HLA is another mechanism to avoid antigen processing and presentation by the tumor." (PMID 37627127, 2023). "One patient’s tumour displayed a homozygous loss-of-function mutation in B2M, resulting in impaired antigen presentation." (PMID 36476325, 2022). "Because the B2M gene is related to T cell immune recognition, its high frequency mutation or deletion makes DLBCL tumor cells insensitive to cytotoxic T cell-mediated killing, suggesting that tumors evade immune surveillance mainly via B2M deletion." (PMID 35280688, 2022). "Previous studies showed that the mutation of HLA class I and B2M in tumor cells is one of important reasons that patients failed ICI treatment in clinic." (PMID 36611830, 2022). "The possible mechanisms of acquired resistance mainly include B2M mutation and loss of HLA heterozygosity, changes in tumor target antigens, and up-regulation of alternative immune checkpoints." (PMID 36304470, 2022). "Beta-2-microglobulin (B2M) is a vital component of human leukocyte antigen class I (HLA-I) molecules, whose mutation inhibits antigen presentation and tumor evasion." (PMID 35069896, 2022).
tumor (continued). "The results presented herein are novel and emphasize the importance of B2M mutation as a mechanism regulating host immune toleration to EBV+ tumor cells which evade immune recognition and escape the T lymphocytes killing in EBV positive DLBCLs." (PMID 36606194, 2022). "Recent studies have proposed several genetic drivers of innate or acquired resistance to ICB therapy, some of which confirm that the B2M gene impedes the success of cancer immunotherapy by generating MHC class I-loss tumor variants." (PMID 36046045, 2022). "The patient experienced PD and new tumor analyses showed loss of B2M protein expression emphasizing the selective pressure of APM negative tumor cells." (PMID 36615128, 2022). "For example, a recombinant adenovirus carrying the B2M gene has been prepared to restore HLA class I expression on tumor cells deficient in B2M." (PMID 36611830, 2022). "It is well known that tumor cells can escape immune surveillance by downregulating or mutating MHC I molecules or β2-microglobulin (B2M)." (PMID 35804881, 2022). "We confirmed loss of MLH1 and B2M protein expression by immunohistochemistry (IHC) in resistant metastatic sites and in a single area of the primary tumor resected 5 years before study entry." (PMID 34715028, 2021). "Studies have shown an association of β2-microglobulin (B2M) mutation with tumor metastases in dMMR/MSI CRCs." (PMID 33467526, 2021). "Other studies also reported similar results and together, indicate that mutation in B2M is associated with suppression of tumor metastasis." (PMID 33467526, 2021). "Mutations in ATLL that help tumor cells avoid immune surveillance include mutations in B2M, HLA-A, HLA-B, CD58, FAS, and PD-1, as well as those interfering with TRAIL-mediated apoptosis and IAP expression." (PMID 34830782, 2021). "Antigen presentation deficiency can also protect tumor cells from being recognized and killed by the immune cells, which includes biallelic B2M mutation and HLA-I down-regulation." (PMID 34194441, 2021). "Correspondingly, B2M-deficient tumor metastasis was found to be significantly targeted by natural killer (NK) cells." (PMID 33658560, 2021). "Truncating alterations, loss of heterozygosity, frameshift mutations, and loss of function alterations in B2M were found in human tumor cells that showed resistance to ICI." (PMID 35582437, 2020). "LOH of B2M was present on the trunk in Tumour 3 and a B2M frameshift mutation was acquired in a subclone, also establishing biallelic B2M loss." (PMID 31949146, 2020). "Beta-2-microglobulin (B2M) is a significant HLA1 molecule whose mutation will hinder tumor antigen presentation and result in therapy resistance." (PMID 32864132, 2020). "Chimeric antigen receptor T cells edited by the CRISPR/Cas9 gene directed against the B2M mutation proposed above can significantly increase anti-tumor activity." (PMID 32000802, 2020). "Here we show that somatic mutations affecting B2M and HLA genes interact with the accumulation of somatic mutations that generate neoantigens during tumor development." (PMID 31345234, 2019). "Mutations in B2M were largely loss of function and more broadly distributed, as expected for a tumor suppressor gene, though several positions were also recurrently mutated." (PMID 31345234, 2019). "We conclude that somatic B2M and HLA mutations are associated with an overall higher burden of neoantigens, supporting the notion that these mutations facilitate tumor immune escape." (PMID 31345234, 2019). "To better understand B2M and HLA mutation timelines, we analyzed the tumor allelic fraction of expressed mutations for all patients." (PMID 31345234, 2019). "B2M mutations tended to occur relatively early during patients’ respective tumor development, whereas HLA mutations were either early or late events." (PMID 31345234, 2019). "Of the 23 tumours with pathogenic B2M mutations, 20 (87%) showed complete loss of B2M expression (sensitivity 87%)." (PMID 31062389, 2019).